Y_RNA (Y RNA )
Gene: Miscellaneous RNA gene on chromosome 3 (41,868,998 to 41,869,095, reverse strand). Ensembl gene ENSG00000251986.
Homologues: Orthologues: chimpanzee Y_RNA (98% identical), guinea pig Y_RNA (86% identical). Paralogues in human: Y_RNA (91% identical), Y_RNA (90% identical), Y_RNA (87% identical), RNY3 (86% identical), Y_RNA (86% identical), RNY3P14 (85% identical), Y_RNA (85% identical), RNY3P1 (84% identical), Y_RNA (84% identical), Y_RNA (83% identical), RNY3P16 (82% identical), RNY3P5 (82% identical), and 92 more.